AQP4 (aquaporin 4)
Diseases named in the same sentence as AQP4 in open-access papers (continued):
Sharing a sentence is not in itself a finding about the gene and the disease.
Cerebral ischemia (continued). "There is accumulating evidence that cerebral ischemia upregulates AQP4 expression, increases BBB permeability, and induces brain edema, which exacerbates ischemic brain injury." (PMID 26952102, 2016). "Following cerebral ischemia, cortical astrocytes exhibit reduced perivascular AQP4 and unchanged AQP4 protein abundance." (PMID 27242440, 2016). "In mice with 1 h transient focal brain ischemia, AQP4 expression is significantly increased at astrocyte endfeet in the lesion core initially and it increases in whole astrocytes at the border of lesion at 48 h." (PMID 27242440, 2016). "For instance, after focal brain ischemia, aquaporin-4 is observed to lose polarized localization to astrocytic end-feet, which is associated with the loss of the astrocyte end-foot anchorage protein β-dystroglycan (DG)." (PMID 27690011, 2016). "Analyses of these results revealed that AQP4 was involved in the formation of brain edema after cerebral ischemia, and SHD treatment reduced AQP4 expression corresponding to its protective effect against brain edema." (PMID 26089944, 2015). "With the AQP4-siRNA technology, it provided further evidence that SHD treatment likely exerts neuroprotective effects following cerebral ischemia mainly via blocking AQP4 channel." (PMID 26089944, 2015). "The degree of Aqp4 polarization is correlated with the magnitude of edema formation following cerebral ischemia." (PMID 26419740, 2015). "All prior studies of Aqp4 in the context of cerebral ischemia and trauma have focused on grey matter astrocytes." (PMID 26419740, 2015). "Following cerebral ischemia, cortical astrocytes exhibited reduced perivascular Aqp4 and unchanged Aqp4 protein abundance." (PMID 26419740, 2015). "The MCAO model, which utilizes focal brain ischemia to impart tissue damage, was previously reported to increase AQP4 expression in the infarct zone shortly after the insult." (PMID 24828425, 2014). "On the contrary, another study in the AQP4 null mouse reported reduced brain swelling and improved neurological outcome following water intoxication and focal cerebral ischemia." (PMID 21408176, 2011). "Reduced brain swelling after cerebral ischemia and water intoxication is also observed in α-syntrophin knock-out mice, which exhibit reduced AQP4 expression in astrocytic foot processes." (PMID 21119879, 2010). "AQP4-null mice are protected from cellular (cytotoxic) brain edema produced by water intoxication, brain ischemia, or meningitis." (PMID 17347837, 2007). "Previous studies have also pointed out that, in the late stage after cerebral ischemia, waste solutes from the necrotic core could leak across the glial scar and be removed by the AQP4-mediated glymphatic pathway in the adjacent tissue." (PMID 40837880, 2025). "Under cerebral ischemia, AQP4 expression on astrocyte membranes is enhanced." (PMID 40353059, 2025). "AQP4 has been proposed to be important for the paravascular (glymphatic) solute flow, and indirect evidence indicates that after brain ischemia, AQP4 may contribute to early brain edema via CSF influx along perivascular spaces." (PMID 38822994, 2025). "The objective of this study was to investigate the specific mechanism of inflammation and apoptosis following cerebral ischemia–reperfusion (I/R) injury using the AQP4-specific inhibitor, N-(1,3,4-thiadiazol-2-yl) pyridine-3-carboxamide dihydrochloride (TGN-020)." (PMID 37695472, 2024). "The relationship between oxidative stress and the activity of AQP4 was also observed in a brain ischemia model, where the treatment with antioxidants such as resveratrol and Edaravone markedly reduced AQP4 protein levels, limiting edema formation and lesion area." (PMID 39043897, 2024). "Moreover, it was reported that Malat1 was highly expressed in OGD/R-induced astrocyte injury models, and that its silencing protected against cerebral ischemia–reperfusion injury by downregulating AQP4 levels via miR-145." (PMID 35991562, 2022).
Cerebral ischemia (continued). "We, therefore, speculated whether the large value on ADCmh represents the high expression of AQP4 which plays a crucial role in cerebral ischemia." (PMID 36605551, 2022). "The expression of AQP4 has been shown to be upregulated after cerebral ischemia." (PMID 35111362, 2022). "It is hypothesized that picroside II can reduce the damage caused by cerebral ischemia to the BBB and nerve cells by downregulating the expression of AQP4." (PMID 36532729, 2022). "In addition, bone marrow MSCs have the ability to maintain the integrity of the BBB by suppressing AQP4 upregulation after cerebral ischemia." (PMID 35454994, 2022). "Some studies have shown that AQP4 knockout can improve the prognosis and neurological function, reduce the infarct volume, increase the survival rate of neurons, and block apoptosis and inflammation after cerebral ischemia." (PMID 35111362, 2022). "Likewise, AQP4 also contributes to the formation and/or the absorption of the brain lump resulting from cerebral ischemia." (PMID 37786741, 2022). "Therefore, we have assessed the early stages of focal cerebral ischemia in a mouse model to highlight the effects of AQP4 on water dynamics." (PMID 36685250, 2022). "AQP4 exacerbates cerebral ischemia by increasing brain edema." (PMID 36710937, 2022). "A study in mice deficient in AQP4 showed that AQP4 inhibition may provide a new therapeutic option for reducing brain edema in a wide variety of cerebral disorders, which suggests that AQP4 could be a potential target for cerebral ischemia." (PMID 36678774, 2022). "It has been reported that targeting AQP4 would result in reduced brain edema and alleviated brain ischemia in which AQP4 knockdown could reduce the cerebellar edema formation, thereby alleviating the acute hypoxic‐ischemic brain injury." (PMID 37786741, 2022). "Borneol inhibits brain edema after cerebral ischemia, which may be related to the downregulation of AQP4 mRNA expression." (PMID 34017247, 2021). "In conclusion, the results of the present study demonstrated that inhibition of MALAT1 could protect against cerebral ischemia/reperfusion injury by downregulating AQP4 levels via miR-145." (PMID 32138732, 2020). "Taken together, our study confirmed that MALAT1 promotes cerebral ischemia-reperfusion injury by affecting AQP4 expression through competitively binding miR-145, indicating that MALAT1 might be a new therapeutic target for treatment cerebral ischemic stroke." (PMID 32138732, 2020). "However, little is known about the molecular mechanisms involved in regulation of presence of AQP4 in perivascular end-feet after brain ischemia." (PMID 32523952, 2020). "Moreover, emodin has been shown to provide a neuroprotective effect against brain ischemia in rats by downregulating expression of AQP4 and Cx43 following IR." (PMID 33167932, 2020). "Here we tested whether Cav-1 regulates AQP4 expression in the perivascular region after brain ischemia in mice." (PMID 32523952, 2020). "Moreover, several miRNAs, such as miR-29b and miR-130a, regulate AQP4 expression in cerebral ischemia." (PMID 29057271, 2017). "Finally, we evaluated AQP4 and mGluR5 expression after cerebral ischemia in a rat model of transient middle cerebral artery occlusion (tMCAO)." (PMID 28503134, 2017). "In remote postconditioning of cerebral ischemia in rats, downregulation of aquaporin 4 (AQP4), which is involved in water homeostasis in astrocytes, may attenuate cerebral damage after transient MCAO." (PMID 28473987, 2017). "Increasing evidence indicates that AQP4 plays an important role in enhancing brain ischemia injury." (PMID 29057271, 2017). "In addition, the AQP4 inhibitor, TGN-020, ameliorated cerebral edema in ischemic mouse brain, while mesenchymal stem cells maintained BBB integrity by inhibiting AQP4 upregulation after cerebral ischemia." (PMID 26952102, 2016). "Aquaporin-4 has been shown as a target gene of miRNA-29b in cerebral ischemia." (PMID 27690011, 2016).
Cerebral ischemia (continued). "Moreover, the results of immunofluorescence staining showed a significant decrease in the expression of GFAP(+)/AQP4(+) cells after cerebral ischemia following EA preconditioning." (PMID 26952102, 2016). "In summary, the effects of AQP4 on cerebral ischemia may be very complex and include several mechanisms." (PMID 27529222, 2016). "Studies on AQP4 expression after cerebral ischemia mainly focus on animal or cell models." (PMID 27529222, 2016). "Accordingly, it can be concluded that AQP4 expression after cerebral ischemia tends to be up-regulated, although the specific change forms may be different due to different models." (PMID 27529222, 2016). "In rat and human cortical astrocytes, perivascular Aqp4 was quickly attenuated following cerebral ischemia, which, in the rat cortical penumbra, was accompanied by unchanged Aqp4 abundance of either the M1 or M23 isoform in either the monomeric or dimeric state." (PMID 26419740, 2015). "Aquaporin-4 (Aqp4) is a passive transmembrane water channel that in the central nervous system (CNS) is exclusively expressed by astrocytes, and is an important molecular contributor to cerebral edema formation after cerebral ischemia." (PMID 26419740, 2015). "This study aimed to investigate neuroprotection of SHD against focal cerebral ischemia/reperfusion (I/R) injury in rats and explore the hypothesis that AQP4 probably is the target of SHD neuroprotection against I/R rats." (PMID 26089944, 2015). "However, AQP4 expression changes depend on the model used; for example, in the rodent model of transient focal brain ischemia, peaks of swelling and AQP4 expression, particularly the M1 isoform, were observed at 1- and 48-hr after ischemia." (PMID 26489685, 2015). "Two studies have shown that ginsenoside Rg1 provides neuroprotection against BBB disruption, edema formation, and neurological injury in rat models of cerebral ischemia/reperfusion through the downregulation of aquaporin 4 expression and anti-apoptosis pathways." (PMID 25620952, 2014). "Treadmill pre-training may reduce cerebral edema and BBB dysfunction during cerebral ischemia/reperfusion injury via the down-regulation of AQP4." (PMID 24416250, 2014). "In addition, observations in AQP4 knock-out mice with water intoxication and focal cerebral ischemia suggested that in vasogenic edema water enters the brain parenchyma independently of AQP4, but exits the brain through AQP4." (PMID 21119879, 2010). "While it is well established that melatonin protects against vasogenic edema resulting from BBB disruption following cerebral ischemia/reperfusion injuries, its potential to modulate post-insult AQP4 activation and thus mitigate cytotoxic edema after ischemic brain injury remains unclear." (PMID 39457496, 2024). "Therefore, MALAT1 affects AQP4 expression by competitively binding to miR-145, thereby promoting cerebral ischemia-reperfusion injury, suggesting that MALAT1 may become a new therapeutic target for the treatment of cerebral ischemic stroke." (PMID 36275741, 2022). "Thus, regulation of AQP4 after cerebral ischemia might provide a therapeutic option for reducing brain edema." (PMID 26952102, 2016). "In a rat model of cerebral ischemia, acute inhibition of AQP4 using TGN‐020 attenuated early cerebral edema, and also inhibited peri‐infarct astrocyte responses and depolarization of AQP4 in the subacute phase, thereby promoting neurological recovery." (PMID 41578884, 2026). "All of these indicate that AE can reduce the expression of aquaporins (AQP3, AQP4, and AQP5) in PSD rats’ brain tissue and alleviate the damage status of depressed rats after cerebral ischemia." (PMID 36982280, 2023). "In rat cerebral ischemia miR-320a inhibits AQP1 and AQP4 expression, whereas anti-miR-320a upregulates AQP1 and AQP4 expression, identifying miR-320a as a potential modulator of these AQPs." (PMID 35036988, 2022).
Cerebral ischemia (continued). "Moreover, it has been indicated that inhibiting AQP4 improved patient outcome and neurological function, reduced infarction volume, increased neuronal survival, and reduced apoptosis and the inflammatory response after cerebral ischemia, which was in accordance with brain edema reduction." (PMID 29057271, 2017). "Moreover, it has been indicated that AQP4 knockout improved outcome and neurological function, reduced infarction volume, increased neuronal survival, and blocked apoptosis and inflammatory response after cerebral ischemia, which is consistent with brain edema reduction." (PMID 29057271, 2017). "Moreover, it was demonstrated AQP4 knockout improved outcome and neurological function, reduced infarction volume, increased neuronal survival, and blocked apoptosis and inflammatory response after cerebral ischemia, which was consistent with brain edema reduction." (PMID 27529222, 2016). "However, as white matter astrocytes differ developmentally, physiologically, and molecularly from grey matter astrocytes, we hypothesized that functionally important regional heterogeneity exists in Aqp4 expression and subcellular localization following cerebral ischemia." (PMID 26419740, 2015). "The aquaporin-4 perivascular pool is identified as the predominant cluster involved in the pathophysiology of cerebral edema after HIBI, with increased aquaporin-4 expression occurring within 48 h after the onset of cerebral ischemia." (PMID 28403909, 2017). "Although RIPC has shown promise in experimental models of cerebral ischemia, it failed to have any influence on AQP4 expression levels and did not confer any significant beneficial effects in an ICH rat model at either 24 or 72 h post-surgery." (PMID 27438832, 2016). "Since AQP4 plays dual roles in the two types of edema and the brain edema of cerebral ischemia during non-acute phase is mixed one, the effects of AQP4 during the phase are complex." (PMID 27529222, 2016). "In addition, mice lacking polarized AQP4 expression also had a reduction of water influx after early cerebral ischemia." (PMID 27529222, 2016). "Notably, in the brains of rats with Parkinson’s disease and cerebral ischemia, MMP-9 not only co-localizes with AQP4 but also an increase in MMP-9 expression results in altered AQP4 polarity, (i.e., “depolarization”), MMP-9 disturbs aquaporin-4 polarization by cleaving β-dystroglycan." (PMID 39295943, 2024). "Thus, we will set more time points across the course of cerebral ischemia to better dynamically access the effects of XFZYD via regulation of AQP4 in the future research and AQP4 knockout mice could be further used to validate the importance of AQP4 and its anchoring proteins." (PMID 36582539, 2022).
Autoimmunity (81 papers, 2008 to 2026). The occurrence of an immune reaction against the organism's own cells or tissues. "These IGHV3 genes have been previously associated with clonal expansions in NMOSD and related autoimmune conditions, implying their involvement in common antigenic responses, potentially including AQP4." (PMID 41246297, 2025). "While these models are able to demonstrate the pathological effects of AQP4-IgG, they fail to recapitulate the autoimmunity underlying NMOSD with production of AQP4 autoantibodies." (PMID 36649074, 2023). "The discrepancy in the findings between these studies and ours suggests that electroporation-mediated immunization is a more efficient method to drive pathogenic AQP4 autoimmunity in rodents." (PMID 36649074, 2023). "AQP4-IgG-positive NMOSD has also been reported in association with other autoimmune disorders such as myasthenia gravis (MG), celiac disease, and autoimmune thyroid disease." (PMID 37022481, 2023). "AQP4 deficiency is associated with pronounced astrogliosis in the CNS including the visual pathway and especially in the retina during CNS autoimmunity." (PMID 35536323, 2022). "Another idea worth noting would be the induction of immune tolerance to the autoantigen by vaccination, as the majority of NMOSD patients have underlying AQP4 autoimmunity with the autoantigen clearly defined." (PMID 36077167, 2022). "Our cohort also supports the observation that NMOSD patients commonly have concomitant markers of autoimmunity, which can add another diagnostic challenge in the setting of equivocal ELISA AQP4 assay results." (PMID 34621549, 2021). "The majority of NMOSD patients are seropositive for IgG autoantibodies against the water channel protein aquaporin-4 (AQP4-IgG), reflecting underlying aquaporin-4 autoimmunity." (PMID 34445343, 2021). "Our findings suggest the possibility that development of AQP4 autoimmunity, the underlying pathogenetic mechanism for AQP4-IgG positive NMOSD in our two patients, involves ectopic GC in their orbital and conjunctival ELF." (PMID 29387055, 2017). "Changes in AQP4 expression in CNS and non-CNS tissue can be regulated by inflammatory mediators induced during and following infection or by underlying autoimmunity and can result in the induction of AQP4-specific lymphocytes and ensuing pathogenesis." (PMID 18510734, 2008). "This study suggests a role of Tfh cells in the pathophysiology of NMOSD in a mouse model with AQP4 autoimmunity and provides an animal model for investigating the immunological mechanisms underlying AQP4 autoimmunity and developing therapeutic interventions targeting autoimmune reactions in NMOSD." (PMID 36649074, 2023). "NMOSD patients seropositive for AQP4-IgG have underlying AQP4 autoimmunity." (PMID 34445343, 2021). "AQP4-IgG positive NMOSD patients have underlying autoimmunity against AQP4." (PMID 34445343, 2021). "When a patient is positive for AQP4 antibody, the decrease in astrocyte numbers may be caused by AQP4 autoimmunity." (PMID 30568655, 2018). "However, AQP4-Ab-positive NMO was recently shown to be frequently associated with other autoimmune disorders, in particular SLE and SS." (PMID 23320783, 2013). "An AQP4 small animal model will permit investigators to examine the following experimental questions: 1) What peripheral or CNS "event" can lead to anti-AQP4 immune responses, and 2) what AQP4 specific immune responses are shaped by infection or underlying autoimmunity that result in NMO?" (PMID 18510734, 2008). "Another means to activate AQP4-specific B cells is bystander activation of AQP4-reactve B cells by the cytokine milieu and associate membrane changes of dendritic cells during infection or autoimmunity that enhance B cell survival and differentiation." (PMID 18510734, 2008).